KCNK5 (potassium two pore domain channel subfamily K member 5)
Description:
K(+) channel that conducts voltage-dependent outward rectifying currents upon membrane depolarization. Voltage sensing is coupled to K(+) electrochemical gradient in an 'ion flux gating' mode where outward but not inward ion flow opens the gate. Homo- and heterodimerizes to form functional channels with distinct regulatory and gating properties.
Synonyms: TASK2; K2p5.1; TASK-2; KCNK5b
Tractability: Small molecule: it belongs to a druggable protein family. Antibody: its Gene Ontology location is reachable by antibodies, with high confidence; UniProt predicts a signal peptide or a membrane-spanning region. PROTAC: ubiquitination databases record sites on it.
Target class: Two-pore domain potassium channel; Voltage-gated ion channel; Ion channel; Potassium channels
Gene: Protein-coding gene on chromosome 6 (39,188,128 to 39,229,559, reverse strand). Ensembl gene ENSG00000164626.
Subcellular location: Membrane
Subcellular location (Human Protein Atlas): Nucleoplasm
Pathways (Reactome):
Muscle contraction: Phase 4 - resting membrane potential
Gene Ontology:
Molecular function: outward rectifier potassium channel activity; potassium channel activity; protein binding; protein heterodimerization activity; potassium ion leak channel activity; voltage-gated potassium channel activity
Biological process: potassium ion transport; potassium ion export across plasma membrane; regulation of resting membrane potential; potassium ion transmembrane transport
Cellular component: plasma membrane; membrane
Genetic constraint (gnomAD): Loss-of-function variants: 19 observed, 37.15 expected, observed/expected ratio (o/e) 0.51, 90% interval 0.36 to 0.75. The upper end of that interval is the gene's LOEUF score, 0.75, which puts it in group 3 of 6, group 1 being the genes least tolerant of losing a copy. Missense variants: 505 observed, 667.15 expected, observed/expected ratio (o/e) 0.76, 90% interval 0.7 to 0.81. Synonymous variants: 276 observed, 284.01 expected, observed/expected ratio (o/e) 0.97, 90% interval 0.88 to 1.07.
Homologues: Orthologues: chimpanzee KCNK5 (99% identical), macaque KCNK5 (99% identical), pig KCNK5 (90% identical), mouse Kcnk5 (89% identical), rat Kcnk5 (88% identical), dog KCNK5 (81% identical), guinea pig KCNK5 (81% identical), tropical clawed frog kcnk5 (59% identical), zebrafish kcnk5a (51% identical), zebrafish kcnk5b (41% identical), Drosophila melanogaster Ork1 (22% identical), Caenorhabditis elegans twk-21 (18% identical), and 11 more. Paralogues in human: KCNK17 (21% identical), KCNK10 (20% identical), KCNK16 (19% identical), KCNK4 (19% identical), KCNK15 (18% identical), KCNK3 (17% identical), KCNK2 (17% identical), KCNK1 (16% identical), KCNK12 (16% identical), KCNK9 (16% identical), KCNK13 (15% identical), KCNK6 (14% identical), and 2 more.
Diseases named in the same sentence as KCNK5 in open-access papers:
KCNK5 is named in the same sentence as 43 diseases in open-access papers, as found by Europe PMC text mining. Sharing a sentence is not in itself a finding about the gene and the disease. The quoted sentences say what the papers report.
migraine (13 papers, 2017 to 2025). "KCNK5, which encodes a potassium channel, is a target candidate for central nervous system illnesses due to its association with migraine and depression sensitivity via related protein family members such as KCNK18 or KCNK4." (PMID 40634879, 2025). "In the GWAS study, ANKDD1B and KCNK5 were associated with migraine and MDD etiology as key genes in neural-related signaling pathways and ion channel regulatory pathways." (PMID 39144710, 2024). "Of the 123 migraine risk loci identified in the most recent and largest GWAS study of migraine, one ion channel gene (KCNK5) was found to be associated with migraine." (PMID 36808568, 2023). "A recent GWA meta study suggested that rs67338227 in the FHL5 gene and rs10456100 in the KCNK5 gene are associated with migraine from 27 population-based cohorts excluding Chinese population." (PMID 33762637, 2021). "A recent genome-wide meta study suggested that rs67338227 in the FHL5 gene and rs10456100 in the KCNK5 gene are associated with migraine from 27 population-based cohorts excluding Chinese population." (PMID 33762637, 2021). "In the combined sample set, SNP rs10456100 (KCNK5) was significantly associated with migraine (χ2 = 37.05, P Value = 9.01 × 10–9)." (PMID 33762637, 2021). "Our aim was to systematically investigate the relationship of common variants in FHL5 and KCNK5 genes with the susceptibility to MO and provide clues as to the nature of the mechanisms involved in the etiology of migraine." (PMID 33762637, 2021). "More studies in future are still needed to investigate the underlying mechanisms of KCNK5 gene and pathology of migraine." (PMID 33762637, 2021). "The four regulatory regions include a CpG island located near the PHACTR1 migraine risk locus and three PREs located near the KCNK5, ASTN2, and RNF213 migraine risk locus." (PMID 32076896, 2020). "Of the same K2P channel subfamily is the protein product of the KCNK5 gene, in which the index SNP defining the migraine risk locus resides." (PMID 32076896, 2020). "Finally, a rare variant with cis-regulatory effects on KCNK5 confers large protection against migraine and brain aneurysms." (PMID 37884687, 2023). "Then, the ion channel KCNK5 gene was identified as a migraine susceptibility locus." (PMID 33762637, 2021). "Interestingly, in the present study, we found that the T allele of SNP rs10456100 was associated with increased risk of migraine and decreased level of KCNK5 gene expression." (PMID 33762637, 2021). "Based on these findings, we hypothesize that this allele might increase extracellular K+ levels by reducing the transcription of the KCNK5 gene, in turn increasing the risk of migraine for individuals." (PMID 33762637, 2021). "Genome-wide association analyses of migraine and its subtypes identify new susceptibility loci, including rare variants with large effects implicating PRRT2, SCN11A and KCNK5." (PMID 37884687, 2023). "Thirdly, the rare intergenic rs72854118-G near KCNK5 and KCNK17 is another variant providing insight into the pathogenesis of migraine." (PMID 37884687, 2023). "Given that MO is the most common subtype of migraine, we conducted this case–control study to evaluate the associations of FHL5 and KCNK5 genes with the risk of MO in a Han Chinese population." (PMID 33762637, 2021). "Locus 2 (intragenic in KCNK5) was recently established as a genome-wide significant locus for migraine." (PMID 28957430, 2017). "In conclusion, our findings indicated that the T allele carriers of SNP rs10456100 and rs7775721 would increase the risk of MO in a Han Chinese population, providing evidence indicating that the KCNK5 and FHL5 genes contribute to the susceptibility of migraine." (PMID 33762637, 2021).
migraine (continued). "Given that migraine without aura (MO) is the most common subtype of migraine, our aim was to systematically investigate the relationship of common variants in FHL5 and KCNK5 genes with the susceptibility to MO and provide clues as to the nature of the mechanisms involved in the etiology of migraine." (PMID 33762637, 2021). "Two have previously been identified as cross-phenotype loci between migraine and CAD (locus 1 in PHACTR1 and locus 3 in AS3MT), while one (locus 2, in KCNK5) is new." (PMID 28957430, 2017). "After considering broadly defined gene-based evidence for association and accounting for 13,524 gene-based tests, two genes especially stood out as meeting the most stringent statistical criteria for genetic features shared between MDD and migraine, ANKDD1B and KCNK5." (PMID 40634879, 2025).
breast carcinoma (8 papers, 2011 to 2025). "Our analysis pinpointed SHC4 and KCNK5 as essential genes within module 11, exhibiting significant correlations with the subtypes of breast cancer." (PMID 39834541, 2024). "E2 induced the overexpression of KCNK5 in luminal breast cancer cells through ERα+, and KCNK5 played an important role in regulating cell proliferation." (PMID 35656548, 2022). "We found that KCNK2 and KCNK5 was downregulated in breast cancer, while KCNK9, KCNK13, and KCNK15 was upregulated in breast cancer." (PMID 35656548, 2022). "The KCNK5 gene encodes TASK-2, a critical potassium channel involved in renal function, and has potential roles in preventing ischemic neurodegeneration and in breast cancer treatment." (PMID 41229886, 2025). "Expression and activity of KCNK5 is up-regulated in some breast cancer cell lines." (PMID 38527087, 2024). "Besides this, ID4, SEMA3F, FOXD, KCNK5, WNK4 and ECM1 associate with chemoresistance origin and SOX5, ITM2A, SNCG, EPHA4, NTS, FGFR2 and ENPEP associate moreover with breast cancer tumorigenesis." (PMID 37239828, 2023). "Breast cancer studies included E1 (KCNMB1), E4 (KCNN3), E9 (KCNH1, KCNK15), E15 (KCNT2), E22 (KCNK5, KCNK15), E33 (KCNQ1-OT1), E38 (KCNMA1), E48 (KCNJ9), and E63 (KCNK12)." (PMID 40867621, 2025). "Overexpression of KCNK5, KCNK9, and KCNK12, as well as reduced expression of KCNK6 and KCNK15, was significantly correlated with triple-negative subtype in breast carcinoma." (PMID 35656548, 2022). "The RNA expression level of KCNK2, KCNK5, KCNK9, KCNK13, and KCNK15 were validated in human breast cancer cell lines." (PMID 35656548, 2022). "Importantly, previous studies have already reported KCNK5 and ABCC11 as prognostic signatures in breast cancer." (PMID 39834541, 2024). "Our results revealed that KCNK9, KCNK13, and KCNK15 was significantly upregulated in breast cancer cell lines including MDA-MB-231 and SK-BR-3 cell lines, while KCNK2 and KCNK5 was downregulated in breast cancer cell lines comparing with breast epithelial cell line MCF-10A." (PMID 35656548, 2022).
deafness (4 papers, 2015 to 2023). An inherited or acquired condition characterized by the complete loss of the ability to hear from one or both ears. "A profound deafness associated with a decrease in endocochlear potential is found in adult Kcnk5−/− mice." (PMID 26549439, 2015).
rheumatoid arthritis (4 papers, 2011 to 2019). A chronic, systemic autoimmune disorder characterized by inflammation in the synovial membranes and articular surfaces. "Expression levels of K2P5.1 (TASK2; KCNK5) channels belonging to the family of two-pore domain potassium channels have previously been correlated to the activity of autoreactive T lymphocytes in patients with multiple sclerosis and rheumatoid arthritis." (PMID 26213925, 2015).
lung carcinoma (2 papers, 2019 to 2020). "In contrast, PROM2 was significantly co-expressed with LAD1, C1ORF106, PVRL4, and KCNK5 in lung cancer." (PMID 31164716, 2020). "Our results suggest that KCNK5 may be used to classify the two lung cancer types under investigation and that this gene is not necessarily only down-regulated in cancer." (PMID 31429720, 2019).
adenoma (1 paper, 2015). A neoplasm arising from the epithelium. "Recently, decreased KCNK5 (TASK-2) expression was identified as a hallmark of aldosterone-producing adenomas, and its transfection into human adrenal cell lines H295R and HAC15 cells resulted in increased aldosterone production." (PMID 25788893, 2015).
Calcium nephrolithiasis (1 paper, 2022). The presence of calcium-containing calculi (stones) in the kidneys. "However, the role of the KCNK5 gene polymorphism in calcium nephrolithiasis has not been fully elucidated." (PMID 35741705, 2022). "Moreover, four SNPs at four loci, rs6667242 at ALPL (p = 0.02999, OR = 0.8331), rs1544935 at KCNK5 (p = 0.01341, OR = 0.7804), rs7328064 at DGKH (p = 0.007452, OR = 1.211) and rs13041834 at BCAS1 (p = 0.03897, OR = 0.8409), were suggestively associated with the risk of calcium nephrolithiasis." (PMID 35741705, 2022). "Moreover, four SNPs at four loci, rs6667242 at ALPL (p = 0.02999, OR = 0.8331), rs1544935 at KCNK5 (p = 0.01341, OR = 0.7804), rs7328064 at DGKH (p = 0.007452, OR = 1.211) and rs13041834 at BCAS1 (p = 0.03897, OR = 0.8409), were suggestively associated with calcium nephrolithiasis." (PMID 35741705, 2022).
coronary artery disease (1 paper, 2019). "KCNK5 is a known coronary artery disease GWAS locus, encoding the potassium two-pore domain channel subfamily K member 5 protein, which is mainly expressed in the cortical distal tubules and collecting ducts of the kidney." (PMID 30547231, 2019).
hearing loss (1 paper, 2015). "KCNK5 specifically found in outer sulcus epithelial cells in connection with root cells might also be involved in presbycusis, since CBA/CaJ mice, which are affected by early age-related hearing loss, show a concomitant loss of cochlear root cells." (PMID 26549439, 2015).
liver cancer (1 paper, 2021). An epithelial or non-epithelial malignant neoplasm that arises from the liver. "KCNK5, a two-pore domain potassium channel, is in the top 1% of underexpressed genes in melanoma and top 5% of underexpressed genes in breast, colorectal, renal, and liver cancers, and there is increasing interest in the role of potassium channels in cancer." (PMID 33482222, 2021).
mastitis (1 paper, 2023). Inflammation of breast tissue during lactation or postpartum due to an obstructed duct or infection. "Moreover, KCNK5, whose abnormal expression level has been associated with mastitis and heat stress in mouse/rat modules, harbored a dMHB signature in its first intron." (PMID 37373515, 2023).
pancreatic ductal adenocarcinoma (1 paper, 2018). An infiltrating adenocarcinoma that arises from the epithelial cells of the pancreas. "An electrophysiological study indicated that KCNK5 was expressed in human pancreatic ductal adenocarcinoma cell line, and the pH‐sensitive K2P subunits coded by KCNK5 were shown to be expressed in pancreatic." (PMID 30334361, 2018).
sleep-disordered breathing (1 paper, 2022). "Several factors have been identified (e.g., sex, polymorphisms in the TASK2/KCNK5, NOTCH4 and CAT genes and pre-term birth) to predict individual vulnerabilities to hypoxia-related sleep-disordered breathing." (PMID 36582343, 2022).
thyroid cancer (1 paper, 2020). "This study implied that KCNK2, KCNK4, KCNK5 and KCNK15 are potential targets of precision therapy for patients with thyroid cancer and these genes are new biomarkers for the therapeutic target for thyroid cancer." (PMID 32742463, 2020). "Besides, we found that KCNK5 and KCNK15, which were highly expressed in thyroid cancer, had a better overall survival rate." (PMID 32742463, 2020). "In summary, by analyzing the differential expression of KCNKs genes, clinical staging analysis, prognosis analysis and functional enrichment analysis, we found that only four genes, KCNK2, KCNK4, KCNK5, and KCNK15, may play a role in the carcinogenesis of thyroid cancer." (PMID 32742463, 2020).
urolithiasis (1 paper, 2022). Stone(s) within the urinary tract. "In a GWAS in the Japanese population, rs1544935 at KCNK5 was identified as being related to risk of urolithiasis and the authors presumed that this variant might promote stone formation by regulating urine pH levels." (PMID 35741705, 2022).
cancer (11 papers, 2013 to 2023). A tumor composed of atypical neoplastic, often pleomorphic cells that invade other tissues. "Previous studies have reported that LAD1, C1ORF106, PVRL4, and KCNK5 are upregulated in cancer cells." (PMID 31164716, 2020). "K2P5.1 (also referred to TASK-2 and KCNK5) plays an important role in cell volume regulation, renal bicarbonate reabsorption, and cancer cell proliferation." (PMID 31861667, 2019). "The data show that mRNA expression of KCNK1, KCNK7, and KCNK9 is upregulated in cancer tissues while KCNK2, KCNK3, KCNK5, KCNK10, KCNK13, KCNK15, and KCNK17 levels are decreased compared to controls." (PMID 31581133, 2019). "One study has found the functional mRNA and protein expression of KCNK5 (gene coding for TASK-2) in PDAC cell lines HPAF, but the role in cancer progression was not further studied." (PMID 33178018, 2020).
tumor (8 papers, 2017 to 2022). "The immunohistochemistry results suggested that the expression of TM4SF1, FASN, and IMPDH1 was significantly elevated in tumor tissue specimens, while the expression of KCNK5 and KCNJ15 was downregulated." (PMID 35480865, 2022). "Compared with tumor-adjacent tissues, KCNK5 and KCNK15 proteins were higher in PTC tissues and KCNK2 and KCNK4 proteins were lower in PTC, especially in PTC cytoplasm." (PMID 32742463, 2020). "Lastly, in order to make the newly obtained knowledge easily accessible to experimental immunologists, we showed the expression of NFAT5, IL2RA, CCR8, BCL6, and KCNK5 in the tumor-infiltrating T cells in a flow cytometric format." (PMID 30061879, 2018). "Hence it is plausible that KCNK5/KCNK9 overexpression related to TN-subtype may be functionally related to specific tumor CpG loci hypomethylation." (PMID 28899398, 2017). "In AK versus normal skin, five SMGs were significantly downregulated in at least two datasets (KIF24, KCNK5, EPB41L, INSIG2, and ABI3BP), suggesting a tumor suppressor role." (PMID 33482222, 2021). "Interrogating published expression datasets against our SMG list found KIF24, KCNK5, EPB41L2, and ABI3BP downregulated in AK compared with those in the normal skin, suggesting tumor suppressor roles." (PMID 33482222, 2021). "Knockdown of BAP18 decreased MYC, CCND1, KCNK5, and FOXC1 mRNA expression in xenograft tumor tissue." (PMID 32986841, 2020). "Moreover, a total of 7 KCNKs were found to be closely related to the tumor stage, which were KCNK1, KCNK2, KCNK5, KCNK6, KCNK7, KCNK19, and KCNK15." (PMID 32742463, 2020). "We did not observe differential expression of KCNK1, KCNK2, or KCNK5 for different tumor grades." (PMID 31581133, 2019).
KCNK5 also shares sentences with these, for which no sentence is quoted: Balkan Endemic Nephropathy (5 papers); inflammatory bowel disease (3); multiple sclerosis (3); autoimmune disease (2); depression (2); Acidosis (1); adrenal adenomas (1); aortic coarctation (1); brain aneurysm (1); cardiac hypertrophy (1); Cerebral ischemia (1); epithelial carcinoma (1); familial hemiplegic migraine (1); melanoma (1); migraine without aura (1); myocardial infarction (1); nephrolithiasis (1); osteosarcoma (1); papillary thyroid carcinoma (1); presbycusis (1); renal fibrosis (1); renal tubular acidosis (1); respiratory depression (1); respiratory failure (1); temporal lobe epilepsy (1); type 2 diabetes (1).